MAP3K21 (mitogen-activated protein kinase kinase kinase 21)
Description:
Negative regulator of TLR4 signaling. Does not activate JNK1/MAPK8 pathway, p38/MAPK14, nor ERK2/MAPK1 pathways.
Synonyms: KIAA1804; MLK4; dJ862P8.3
Tractability: Small molecule: a structure with a bound ligand is known; a high-quality ligand is known; it belongs to a druggable protein family. Antibody: the Human Protein Atlas places it where antibodies can reach. PROTAC: it is named in the literature on targeted protein degradation; ubiquitination databases record sites on it; a small molecule that binds it is known.
Target class: Enzyme; Transferase
Gene: Protein-coding gene on chromosome 1 (233,327,714 to 233,385,281, forward strand). Ensembl gene ENSG00000143674.
Subcellular location (Human Protein Atlas): Cytosol; Plasma membrane
Gene Ontology:
Molecular function: protein binding; JUN kinase kinase kinase activity; protein homodimerization activity; ATP binding; MAP kinase kinase kinase activity; protein kinase activity; protein serine kinase activity
Biological process: protein phosphorylation; MAPK cascade
Genetic constraint (gnomAD): Loss-of-function variants: 57 observed, 66.99 expected, observed/expected ratio (o/e) 0.85, 90% interval 0.69 to 1.06. The upper end of that interval is the gene's LOEUF score, 1.06, which puts it in group 4 of 6, group 1 being the genes least tolerant of losing a copy. Missense variants: 1,193 observed, 1,197.9 expected, observed/expected ratio (o/e) 1, 90% interval 0.95 to 1.04. Synonymous variants: 552 observed, 486.37 expected, observed/expected ratio (o/e) 1.13, 90% interval 1.06 to 1.22.
Homologues: Orthologues: chimpanzee MAP3K21 (99% identical), macaque MAP3K21 (95% identical), rabbit MAP3K21 (83% identical), pig MAP3K21 (81% identical), dog MAP3K21 (79% identical), guinea pig MAP3K21 (69% identical), mouse Map3k21 (68% identical), rat Map3k21 (67% identical), zebrafish map3k21 (58% identical). Paralogues in human: MAP3K9 (50% identical), MAP3K10 (44% identical), MAP3K11 (38% identical), MAP3K13 (23% identical), MAP3K12 (21% identical), MAP3K20 (14% identical), TNNI3K (13% identical), BRAF (12% identical), LRRK2 (12% identical), RAF1 (12% identical), TESK1 (12% identical), TESK2 (12% identical), and 11 more.
Diseases named in the same sentence as MAP3K21 in open-access papers:
MAP3K21 is named in the same sentence as 28 diseases in open-access papers, as found by Europe PMC text mining. Sharing a sentence is not in itself a finding about the gene and the disease. The quoted sentences say what the papers report.
breast carcinoma (4 papers, 2019 to 2025). "Analysis of multiple datasets indicates that high expression of MAP3K21 is associated with a poor survival in breast cancer, and, the C allele of rs1294255 is associated with a low expression of MAP3K21." (PMID 31921621, 2019). "Both MAP3K21 and PCNX2 have no previous evidence of an effect in the vasculature, but have an implicated role in cancers, such as breast cancer metastasis, glioblastomas (MAP3K21), and thyroid cancer (PCNX2)." (PMID 40013929, 2025).
cervical cancer (2 papers, 2023 to 2024). A primary or metastatic malignant neoplasm involving the cervix. "ARHGEF6 has been linked to T cell migration in lung cancer, while MAP3K21 (or MLK4) has also been implicated in immune infiltration in cervical cancer." (PMID 38777088, 2024).
colorectal cancer (2 papers, 2023 to 2024). A primary or metastatic malignant neoplasm that affects the colon or rectum. "Entirely new predictions include MAP3K21 (encoding a mixed-lineage kinase) in colorectal cancer, USP17L22 (encoding a deubiquitinating enzyme) in breast ductal carcinoma and TPTE (encoding a tyrosine phosphatase) in lung adenocarcinoma." (PMID 38890488, 2024).
breast tumors (1 paper, 2019). "MAP3K21 rs1294255 was associated with lymph-node invasion of breast tumors." (PMID 31921621, 2019).
lymph node metastasis (1 paper, 2019). "A decreased risk of lymph node metastasis was associated with the MAP3K21 rs1294255-C allele, particularly in rs1294255-GC (OR = 0.47; P = 0.001)." (PMID 31921621, 2019).
parasitic infection (1 paper, 2020). "Genetic variants of interest identified in several immune related genes for all the antibody response and parasitic infection traits: IBDV (TOLLIP, ANGPTL5, BCL9, THEMIS2), MDV (GRM7), SG (MAP3K21), Eimeria (TOM1L1), and cestodes (TNFAIP1, ATG9A, NOS2)." (PMID 33193617, 2020).
cancer (12 papers, 2019 to 2026). A tumor composed of atypical neoplastic, often pleomorphic cells that invade other tissues. "The MLK4 gene (MAP3K21/KIAA1804) is frequently mutated and overexpressed in various types of human cancer." (PMID 37594950, 2023). "Another example of bioinformatics guiding the identification of novel cancer‐associated kinases enriched in predicted pathogenic mutations comes from the study of mixed‐lineage kinase 4 (MLK4 encoded by MAP3K21)." (PMID 30548122, 2019). "Large-scale genomic and transcriptomic data indicated that the MLK4 gene (MAP3K21/KIAA1804) is frequently mutated and overexpressed in different types of human cancer." (PMID 34839359, 2021). "In the pan-cancer analyses, we identified MLK4 (also known as MAP3K21; q = 2 × 10−4)—a mixed lineage kinase that regulates the JNK, P38 and ERK signalling pathways and has been reported to inhibit tumorigenesis in colorectal cancer." (PMID 31645765, 2019).
tumor (9 papers, 2019 to 2026). "Additional analysis of TCGA tumor samples indicated that MLK4 mRNA overexpression was highly concordant with increased copy number for the MAP3K21 gene, particularly in TNBC." (PMID 30552384, 2019).
infection (1 paper, 2020). The state of being infected such as from the introduction of a foreign agent such as serum, vaccine, antigenic substance or organism. "Therefore, the down-regulation and hypermethylation of MAP3K21 after ETEC F4ac infection may be to maintain balance of the inflammatory response." (PMID 32547963, 2020). "Considering the functions of these genes, we believe that MAP3K21, PAK6, and MPZL1are strongly correlated with diarrhea induced by ETEC F4ac infection." (PMID 32547963, 2020).
MAP3K21 also shares sentences with these, for which no sentence is quoted: glioma (5 papers); glioblastoma (4); triple-negative breast carcinoma (3); cervical squamous cell carcinoma (2); lung adenocarcinoma (2); lung carcinoma (2); metastatic tumors (2); anaplastic astrocytoma (1); breast ductal carcinoma (1); colon cancer (1); endocervical adenocarcinoma (1); gastric cancer (1); invasive breast carcinoma (1); melanoma (1); oligodendroglioma (1); ovarian carcinoma (1); polyp (1); prostate carcinoma (1); thyroid cancer (1).